FTO (FTO alpha-ketoglutarate dependent dioxygenase)
Diseases named in the same sentence as FTO in open-access papers (continued):
Sharing a sentence is not in itself a finding about the gene and the disease.
lung cancer (56 papers, 2017 to 2025). A malignant neoplasm involving the lung. "In this study, we investigated the role of the RNA demethylase fat mass and obesity‐associated protein (FTO) in lung cancer progression and determined the underlying molecular mechanisms." (PMID 40621649, 2025). "Taken together, these in vitro results are consistent with the in vivo observations and support a role for FTO in promoting malignant behaviours associated with lung cancer progression." (PMID 40621649, 2025). "The results of our study provide valuable insights into the FTO–IGFBP3–AKT signalling axis in lung cancer, highlighting its potential as a diagnostic, prognostic, and therapeutic target." (PMID 40621649, 2025). "We confirmed that an excess of nuclear expression of FTO in EGFR-TKI-resistant NSCLC cells is associated with the development of the EGFR TKI resistance in lung cancer cells." (PMID 40722726, 2025). "For instance, Fuks found that down-regulated FTO in epithelial cancers such as lung cancer was associated with a worse prognosis, and FTO deficiency augmented the EMT program through increased m6A signals of key mRNAs within the Wnt signaling cascade." (PMID 37437245, 2023). "It has been confirmed that RNA methyltransferases such as WTAP and METTL3 and RNA demethylases such as ALKBH5 and FTO are intimately associated with destructive lung diseases, including different types of lung cancer." (PMID 37936118, 2023). "Further bioinformatics analysis showed that higher expression levels of FTO and A3B were associated with significantly worse overall survival in lung cancer patients." (PMID 36233132, 2022). "Generally, the overexpression of FTO associated with decreased m6A promotes tumor formation in lung cancer." (PMID 34381710, 2021). "Additionally, high expression of FTO was associated with late-stage lung cancer as seen by Fisher’s exact test (p = 0.01)." (PMID 40722726, 2025). "Furthermore, a genetic variant of the FTO gene (rs9939609), which is associated with greater body weight, has been associated with lower lung cancer risk." (PMID 38037323, 2023). "Similarly, functional loss studies have shown that FTO knockdown can effectively inhibit lung cancer cell line proliferation and invasion." (PMID 34381710, 2021). "Our results revealed low expression levels of both ALKBH5 and FTO in lung cancer tissues, with ALKBH5 being the sole enzyme showing negative regulation of HMMR." (PMID 39990663, 2025). "Late-stage lung cancer tissues had statistically significantly (p = 0.01) higher FTO expression compared to early-stage tissues by both imaging study and pathology grading." (PMID 40722726, 2025). "In lung cancer tissues, elevated expression of FTO and ALKBH5 promotes tumor cell proliferation, with m6A modifications playing a crucial role." (PMID 40916616, 2025). "This analysis confirmed that FTO was expressed at significantly higher levels in both human and mouse lung cancer tissues than in adjacent normal tissues." (PMID 40621649, 2025). "These demethylases regulate lung cancer progression and our study found that loss of METTL3 and FTO is linked to worse prognoses in LUAD." (PMID 40916616, 2025). "To investigate the role of FTO‐mediated regulation of IGFBP3 in lung cancer progression, we first compared FTO and IGFBP3 transcript levels in paired tumour and adjacent normal tissues from 36 LUAD patients." (PMID 40621649, 2025). "Firstly, we successfully established patient‐derived lung cancer organoid models and performed FTO gene knockdown using a constructed shRNA lentiviral vector." (PMID 40621649, 2025). "A previous study revealed that FTO downregulation resulted in suppression of lung cancer cell proliferation and colony formation." (PMID 40722726, 2025). "To investigate the role of RNA demethylases in the regulation of cell differentiation in lung cancer, we depleted the two known m6A RNA demethylases, FTO and ALKBH5, in two different human LUAD cell lines: A549 and H358." (PMID 41301413, 2025).
lung cancer (continued). "In our study, we also found FTO to be a potential prognostic marker for lung cancer patients, as the immunohistochemistry studies showed a significant correlation between FTO expression and the stage of lung cancer." (PMID 40722726, 2025). "Further research has established that FTO plays a critical role in modulating the growth and invasiveness of lung cancer cells by influencing mRNA stability and translation efficiency." (PMID 40646807, 2025). "Collectively, we revealed that FTO drives lung cancer progression via m6A‐dependent sequestration of IGFBP3 mRNA into P‐bodies by IMP3, which suppresses translation and activates AKT signalling." (PMID 40621649, 2025). "Because the expression patterns and regulatory mechanisms of FTO in lung cancer are poorly understood, we undertook a comprehensive investigation of FTO expression in LUAD and the molecular mechanisms of action that contribute to disease progression." (PMID 40621649, 2025). "To further investigate the cellular functions of FTO in lung cancer, we transduced the human LUAD cell lines A549 and PC9 with lentiviruses encoding negative control (NC) or FTO‐specific shRNA." (PMID 40621649, 2025). "To confirm these findings and additionally validate the KrasG12D mouse model of lung cancer for mechanistic investigations, we generated KrasG12D; FTOfl/fl mice, in which FTO was specifically deleted in alveolar epithelial cells." (PMID 40621649, 2025). "Significantly, FTO continues to foster the progression of lung cancer, bladder cancer, and thyroid cancer, despite its down-regulation at the RNA level." (PMID 39449798, 2024). "Like ALKBH5, FTO is downregulated as a tumor suppressor in a variety of cancers, including BC, lung cancer, CRC, bladder cancer, prostate cancer, ccRCC, and adrenocortical cancer." (PMID 37007161, 2023). "In examining the genes with the highest fold change in expression between ciliated cells from healthy and IPF tissue, IPF ciliated cells were found to highly express FTO and NEAT1, both markers implicated in lung cancer development." (PMID 35326483, 2022). "Collectively, these findings suggest an important role of the FTO/m6A axis in arsenic-induced mutagenesis and lung cancer in general as well." (PMID 36233132, 2022). "FTO activates cell migration through m6A demethylation, thereby promoting lung cancer cell progression." (PMID 35186164, 2022). "FTO has a pro-tumorigenic role in lung cancer, as evident from its overexpression in lung cancer tissues and cell lines." (PMID 35409166, 2022). "More recently, downregulation of FTO reduced lung cancer cell proliferation and invasion and promoted cell apoptosis." (PMID 34367534, 2021). "We also tested the expression of m6A writers METTL3, METTL14, and WTAP and of erasers ALKBH5 and FTO after the treatment of IL-37 in A549 cells and lung cancer tissues." (PMID 33489865, 2020). "The knockdown of FTO inhibits the proliferation of lung cancer cells by modulating the mRNA stability of USP7 via FTO‐mediated m6A demethylase." (PMID 33029866, 2020). "FTO promoted the proliferation, colony formation ability of lung cancer cells in vitro, and promoted lung cancer cell growth in vivo." (PMID 33304380, 2020). "We also showed the expression of m6A writers METTL3, METTL14, and WTAP and erasers ALKBH5 and FTO in A549 cells and lung cancer tissues after the treatment of IL-37." (PMID 33489865, 2020). "On the other hand, high expression of FTO in lung cancer was found to decrease the m6A levels of ubiquitin-specific peptidase 7 (USP7), improve the mRNA stability of USP7, and promote the occurrence of NSCLC." (PMID 32398132, 2020). "Furthermore, the expression of FTO in both early and late-stage lung cancer, as well as its correlation with patient survival using a Kaplan–Meier curve, has yet to be investigated." (PMID 40722726, 2025).
lung cancer (continued). "However, our current study revealed a pattern, where FTO upregulation promotes lung cancer growth and migration." (PMID 40722726, 2025). "Overexpression of FTO in lung cancer cells could also enhance myeloid zinc finger protein 1 (MZF1) expression leading to oncogenesis." (PMID 40722726, 2025). "In this investigation, we explored the role of FTO in lung cancer tumorigenicity." (PMID 40722726, 2025). "In lung cancer, FTO downregulation increases m6A levels which then mediates downregulation of MZF1, a myeloid zinc finger protein 1 and USP7, ubiquitin-specific protease 7 due to decreased stability of their mRNA transcripts, causing an increase in lung cancer tumorigenicity." (PMID 40722726, 2025). "FTO expression might have a significant prognostic value to differentiate the early stage from more advanced stages of lung cancer." (PMID 40722726, 2025). "We next sought to unravel some of the downstream events that mediate FTO functions in lung cancer." (PMID 40621649, 2025). "Individuals with lung cancer have been observed to show elevated expression of FTO." (PMID 40722726, 2025). "Thus, IGFBP3 acts as a functional downstream target of FTO in regulating AKT activity in lung cancer." (PMID 40621649, 2025). "FTO upregulation in EGFR TKI lung cancer cells indicates that FTO could promote tumorigenesis of resistant cells." (PMID 40722726, 2025). "Several studies have also supported FTO’s oncogenic role in lung cancer." (PMID 40722726, 2025). "Moreover, IHC studies on early- and late-stage lung tumors shed light on FTO’s role in lung cancer tumorigenicity and its role as a prognostic marker." (PMID 40722726, 2025). "However, increasing evidence suggests that m6A demethylases FTO and ALKBH5 are frequently overexpressed in lung cancer and significantly associated with the tumor’s prognosis." (PMID 38094306, 2023). "By analyzing lung tissue microarray data, it was found that expression levels of FTO and A3B were significantly higher in human lung cancer tissues than the adjacent normal lung tissues, and there was a significant positive correlation between FTO and A3B expression in lung cancer." (PMID 36233132, 2022). "The m6a demethylase FTO affects the growth of lung cancer by regulating USP7 m6a methyltransferase." (PMID 35872842, 2022). "Generally, in lung cancer, FTO is elevated to promote proliferation and invasion." (PMID 34895230, 2021). "However, studies have revealed that FTO as an m6A demethylase participates in promoting the growth of lung cancer cells in vitro." (PMID 34367534, 2021). "Besides, the results of Kaplan–Meier plotter analysis also indicate that low FTO expression is related to worse OS of lung cancer patients." (PMID 34367534, 2021). "Furthermore, we further found low FTO expression was closely related to poor OS of lung cancer patients by using Kaplan–Meier plotter." (PMID 34367534, 2021). "However, the function of FTO in lung cancer remains to be explored, and we are now focusing on this issue." (PMID 33879631, 2021). "However, up to now, in lung cancers, only FTO and METTL3 have been reported as potential targets for its diagnosis and treatment 31,32." (PMID 32398949, 2020). "For example, FTO could promote the progression of lung carcinoma by releasing the m6A modification in MZF1 mRNA and strengthening its stability." (PMID 33553151, 2020). "Indeed, the percentage of m6A‐modified RNA was significantly lower in tumour tissues compared with adjacent non‐tumour tissues, whereas m6Am levels were not significantly different; these results are consistent with an m6A‐specific and ‐dependent role for FTO in lung cancer proliferation." (PMID 40621649, 2025). "For example, meclofenamic acid, an FTO inhibitor, restores gefitinib sensitivity in non‐small cell lung cancer, and the combination of rhein (another FTO inhibitor) with tyrosine kinase inhibitors (TKIs) may benefit tyrosine kinase inhibitor‐resistant cancer patients." (PMID 37667528, 2023).
lung cancer (continued). "In addition, USP7 gene knockout or drug suppression (P5091 or P22027) reduced the proliferation rate and colony-forming ability of lung cancer cells, while the inhibitory effect of FTO gene knockout on the growth of lung cancer cells was restored by excessive USP7 expression." (PMID 33952279, 2021). "All these indicate that FTO may be a potential therapeutic target in lung cancer." (PMID 33029866, 2020). "FTO is also recognized as a crucial gene that interferes with the m6A modification of E2F1 48, and overexpression of FTO has been found to decrease m6A levels in E2F1, highlighting its critical role in the progression of lung cancer." (PMID 41281757, 2025). "In lung cancer, Wnt signaling induces EZH2 to form a protein complex with β-catenin and bind the LEF/TCF binding element in the FTO promoter region." (PMID 37007161, 2023). "Recent studies have highlighted the importance of FTO and ALKBH5, as erasers involved in m6A RNA demethylation, in the development of lung cancer." (PMID 38094306, 2023). "To investigate how m6A is regulated in KL lung cancer, we compared the expression of proteins that act as the m6A writer complex (METTL3, METTL14, and WTAP) and erasers (ALKBH5 and FTO)." (PMID 34016959, 2021). "The results showed that the expression profiles of eight m6A regulators (ALKBH5, FTO, HNRNPC, METTL14, RBM15, YTHDC1, YTHDC2, and ZC3H13) were significantly different among the three different lung cancer subtypes (P < 0.01)." (PMID 34805165, 2021). "To determine whether FTO regulates LUAD behaviour through its m6A demethylase activity, we quantified the proportion of m6A of total RNA in 26 paired tissues from lung cancer patients using an ELISA." (PMID 40621649, 2025). "Taken together, these findings support the hypothesis that FTO‐ and m6A‐mediated regulation of IGFBP3 leads to activation of the AKT pathway through an IGF‐independent mechanism, thereby contributing to lung cancer progression." (PMID 40621649, 2025). "m6A regulators, including METTL3, FTO, and IGF2BP2, act as tumor promoters through the C-myc pathway in an m6A-dependent manner to promote the growth, invasion, migration, and progression of various tumors, such as BC, lung cancer, and GC." (PMID 39199429, 2024). "Mechanistically, FTO can decrease m6A levels through its demethylase activity, enhance the stability of ubiquitin-specific protease (USP7) mRNA, and promote the growth of lung cancer cells." (PMID 38094306, 2023). "Furthermore, we will discuss future directions of research in this field and explore the potential clinical applications of targeting of FTO and ALKBH5 in the treatment of lung cancer." (PMID 38094306, 2023). "FTO and ALKBH5 are known to be upregulated in lung cancer tissues." (PMID 38094306, 2023). "FTO wildtype overexpression, but not its mutant enzymatically-inactive forms, promoted oncogenic functions in lung cancer cells, including proliferation, invasion, and colony formation ability." (PMID 35409166, 2022). "Notably, exosomal-FTO facilitated ABCC10 of recipient cells via FTO/YTHDF2/ABCC10 axis, eventually leading to gefitinib resistance in non–small cell lung cancer (NSCLC)." (PMID 36517820, 2022). "Existing literature has shown that depletion of FTO effectively suppressed the proliferative and invasive potential of cells, and FTO increased MZF1 expression by demethylating MZF1 mRNA to play its oncogenic role in lung cancer." (PMID 33533172, 2021). "Specifically, FTO can erase the m6A in ubiquitin specific peptidase 7 (USP7) and myeloid zinc finger 1 (MZF1) mRNAs, resulting in USP7 and MZF1 overexpression, which function as oncogenes in lung cancer." (PMID 34895230, 2021). "Furthermore, FTO enhanced the expression of myeloid zinc finger 1 (MZF1) by reducing the m6A level in MZF1 mRNA and enhancing its stability, thus promoting the development of lung cancer." (PMID 32398132, 2020).
colorectal cancer (54 papers, 2020 to 2025). A primary or metastatic malignant neoplasm that affects the colon or rectum. "Gholamalizadeh's study focused on the relationship between FTO polymorphisms and colorectal cancer, thereby broadening the scope of research on FTO across different cancer types." (PMID 40391584, 2025). "In colorectal cancer, by contrast, FTO protein can be down-regulated and associate with poor prognosis, underscoring that FTO’s checkpoint consequences are not uniform across tissues." (PMID 41280938, 2025). "Hypoxia in the tumor microenvironment, which causes FTO to be degraded by ubiquitination, is linked to a poor prognosis for people with colorectal cancer." (PMID 40919129, 2025). "ZBTB48 ablation also accelerates growth of HCT-116 colorectal cancer cells and modulates FTO-dependent regulation of Metastasis-associated protein 1 (MTA1) transcripts by controlling the binding to MTA1 mRNA of the m6A reader IGF2BP2." (PMID 39300486, 2024). "Recent studies have linked FTO-mediated m6A/m6Am demethylation to modulation of the stem-like properties of colorectal cancer (CRC) cells, as well as to CRC metastasis." (PMID 39300486, 2024). "Logistic regression of the association between colorectal cancer and dietary intake among people with TT genotype of FTO rs9939609 polymorphism." (PMID 37545585, 2023). "Previous research has evaluated the link between FTO SNPs (single nucleotide polymorphisms) and carcinogenesis within prostate, pancreatic, breast and colorectal cancer." (PMID 36718644, 2023). "Logistic regression of the association between colorectal cancer and dietary intake among people with AA/AT FTO rs9939609 genotype." (PMID 37545585, 2023). "Specifically, there is a positive association between colorectal cancer and rs1558902, rs8050136, rs3751812, rs9939609 FTO SNPs in Japanese population and the A allele of rs9939609 FTO SNP in Iranian population." (PMID 36874096, 2023). "In this study, patients with colorectal cancer were assessed for the interactions between FTO gene polymorphisms and dietary intake." (PMID 37545585, 2023). "FTO is a m6A demethylase that promotes breast tumor progression by inhibiting BNIP3, whereas another study reported inhibitory effect of FTO on metastasis by targeting demethylating metastasis-associated protein 1 (MTA1) mRNA in colorectal cancer." (PMID 35090515, 2022). "On the other hand, FTO gene polymorphisms can increase the risk of colorectal cancer through the effect on body weight." (PMID 36263301, 2022). "Logistic regression of the association between colorectal cancer and dietary fiber intake among people with AA/AT FTO rs9939609 genotype." (PMID 36263301, 2022). "For example, one study found that rs1558902, rs8050136, rs3751812, and rs9939609 FTO SNPs had a positive association with colorectal cancer in Japanese population." (PMID 36263301, 2022). "The present study investigated the genetic association of FTO rs9939609 variant with the risk of developing colorectal cancer in 375 Iranians (125 patients and 250 healthy) volunteers." (PMID 34650918, 2021). "This study aims to evaluate the relationship between FTO rs9939609 polymorphism and colorectal cancer (CRC) in Iranian people." (PMID 34650918, 2021). "The occurrence of AA genotype of FTO rs9939609 polymorphism in the colorectal cancer patients was significantly higher compared to that of healthy subjects (16.4 vs. 2.9%, respectively, P=0.02)." (PMID 34650918, 2021). "Here, we show that the cytoplasmic pool of fat mass and obesity-associated protein (FTO) impedes CSC abilities in colorectal cancer through its N6,2’-O-dimethyladenosine (m6Am) demethylase activity." (PMID 33741917, 2021). "The present case‐control study identified the genetic association of FTO rs9939609 variant with colorectal cancer in Iranians with the A allele over-represented in the patient group." (PMID 34650918, 2021).